LUADT1 (lung adenocarcinoma associated transcript 1)
Gene: Long non-coding RNA gene on chromosome 6 (147,158,925 to 147,180,992, forward strand). Ensembl gene ENSG00000196634.
Diseases named in the same sentence as LUADT1 in open-access papers:
LUADT1 is named in the same sentence as 9 diseases in open-access papers, as found by Europe PMC text mining. Sharing a sentence is not in itself a finding about the gene and the disease. The quoted sentences say what the papers report.
lung adenocarcinoma (4 papers, 2015 to 2021). A carcinoma that arises from the lung and is characterized by the presence of malignant glandular epithelial cells. "The latest research reports that transcript 1 (LUADT1)-associated lung adenocarcinoma is a carcinogenic lncRNA, which promotes lung adenocarcinoma cell proliferation by inhibiting p27 epigenetics." (PMID 34738862, 2021). "Lung adenocarcinoma associated transcript 1 (LUADT1) has been reported as an oncogenic long non-coding RNA (lncRNA) in lung adenocarcinoma, while its roles in small cell lung cancer (SCLC) are unknown." (PMID 31842825, 2019). "It was observed that LUADT1 downregulated P27 by epigenetic pathway, thereby upregulating and promoting the proliferation of lung adenocarcinoma cells." (PMID 33225891, 2020). "In lung adenocarcinoma, LUADT1 regulates the expression of p27 through epigenetic pathways to promote cancer cell proliferation." (PMID 31842825, 2019). "The oncogenic role of the newly identified lncRNA LUADT1 has been revealed in lung adenocarcinoma." (PMID 33225891, 2020). "The function of LUADT1 has only been investigated in lung adenocarcinoma." (PMID 33225891, 2020). "LUADT1 is a newly identified oncogenic gene long non-coding RNA (lncRNA) in lung adenocarcinoma." (PMID 33225891, 2020).
lung carcinoma (3 papers, 2015 to 2019). "In another cohort of 78 lung cancer patients, we investigated the expression level of LUADT1 and analyzed its clinical correlation." (PMID 26291312, 2015). "The LUADT1 (ENSG00000196634) gene is located at chromosomal locus 6q24.3 locus, which is within the lung cancer susceptibility locus 6q23-6q25,29, 30 and is transcribed as a 453nt lncRNA." (PMID 26291312, 2015). "Quantitative real-time PCR (qRT-PCR) was utilized to profile LUADT1 expression in lung cancer cell lines." (PMID 26291312, 2015). "For lung cancer, various lung cancer-specific lncRNAs have been identified, such as MALAT1, TARID, and LUADT1." (PMID 27154193, 2016).
colorectal cancer (2 papers, 2018 to 2022). A primary or metastatic malignant neoplasm that affects the colon or rectum. "The Lung Adenocarcinoma Associated Transcript 1 (LUADT1) is a known lncRNA exerting oncogenic properties in colorectal cancer and melanoma, located on 6q24.3 locus." (PMID 36290744, 2022). "These include but are not restricted to lncRNAs like HOTAIR, Pvt1, RoR, prostate cancer–associated transcript 1 (PCAT1), ANRIL, H19, nuclear enriched abundant transcript 1 (NEAT1), UCA1, lung adenocarcinoma transcript 1 (LUADT1), colorectal cancer–associated lncRNA (CCAL), and many more." (PMID 30296263, 2018).
nasopharyngeal carcinoma (2 papers, 2021 to 2024). A carcinoma arising from the nasopharyngeal epithelium. "One lncRNA named lung adenocarcinoma-related transcript 1 (lncRNA LUADT1) has been revealed to involve in nasopharyngeal carcinoma (NPC) progression." (PMID 38226210, 2024).
Sepsis (1 paper, 2020). Sepsis is defined as life-threatening organ dysfunction caused by a dysregulated host response to infection. "It was observed that the expression levels of LUADT1 were significantly lower in sepsis patients then that in the control group (p < 0.05)." (PMID 33225891, 2020). "This study was therefore carried out to investigate the potential interaction between LUADT1 and miR-195 in sepsis." (PMID 33225891, 2020). "The expression of LUADT1 was detected in plasma from both sepsis patients (n = 60) and healthy controls (n = 60)." (PMID 33225891, 2020). "The results showed that the expression levels of LUADT1 were significantly and inversely correlated with the expression levels of miR-195 in sepsis patients (R2 = 0.0699, p < 0.05), while the expression levels of Pim-1 were positively correlated with that of LUADT1 (R2 = 0.1412, p < 0.05)." (PMID 33225891, 2020). "In conclusion, LUADT1 is downregulated in sepsis and may regulate the miR-195/Pim-1 axis to inhibit the apoptosis of HCAECs induced by LPS." (PMID 33225891, 2020). "This study was carried out to investigate the role of LUADT1 in sepsis." (PMID 33225891, 2020). "In summary, LUADT1 may protect cardiac endothelial cells against apoptosis in sepsis by regulating the miR-195/Pim-1 axis." (PMID 33225891, 2020). "We found that LUADT1 was downregulated in sepsis and might regulate the miR-195/Pim-1 axis to inhibit LPS-induced of HCAEC apoptosis." (PMID 33225891, 2020). "Thus, LUADT1 may serve as a potential therapeutic drug for protecting patients’ hearts through the treatment of sepsis." (PMID 33225891, 2020).
tumor (4 papers, 2015 to 2021). "Using this approach, we characterized a novel lncRNA, LUADT1, because its network included multiple protein-coding genes associated with tumor growth, invasion or prognosis." (PMID 26291312, 2015). "Comparing to non-tumor samples, significantly higher expression levels of LUADT1 were observed in SCLC tissues (p < 0.05)." (PMID 31842825, 2019). "The silence of LUADT1 induced cell cycle arrest and significantly inhibited tumor growth both in vivo and in vitro." (PMID 26291312, 2015). "Our RNA interaction bioinformatics prediction showed that LUADT1 could form strong base pairing with miR-15a-3p, which is a tumor-suppressive miRNA that can target Twist1." (PMID 31842825, 2019). "We next examined whether the tumor cell cycle was affected after LUADT1 knockdown by Annexin V and propidium iodide double staining via FACS analysis." (PMID 26291312, 2015). "Levels of LUADT1 in two types of tissues (SCLC and non-tumor) were measured and compared by qPCR and paired t-test, respectively." (PMID 31842825, 2019). "In addition, lncRNA BANCR exerts tumor-suppressive functions in NSCLC cells, while HOTAIR, MALAT1, LUADT1 and AFAP1-AS1 et.al exert oncogenic function in NSCLC." (PMID 26840083, 2016). "To test whether LUADT1 regulates LUAD cell proliferation in vivo, we established xenograft tumor models in nude mice using A549 cells transfected with scrambled shRNA or shLUADT1." (PMID 26291312, 2015). "The LUADT1 expression level was significantly higher in LUAD than in LSCC (P=0.019) and correlated with the tumor stage (P=0.043), but not with N stage or TNM stage." (PMID 26291312, 2015).
cancer (3 papers, 2019 to 2021). A tumor composed of atypical neoplastic, often pleomorphic cells that invade other tissues. "We also provided evidence that LUADT1 may sponge miR-15a-3p to upregulate Twist1, thereby promoting cancer cell invasion and migration." (PMID 31842825, 2019). "In addition, LUADT1 may sponge miR-15a-3p to upregulate Twist1, thereby promoting cancer cell invasion and migration." (PMID 31842825, 2019). "LncRNA LUADT1, ZDHHC8P1, JPX, LINP1 and AGAP2‐AS1 have been reported to participate in the development of cancers." (PMID 34547170, 2021). "We found that LUADT1 was upregulated in NSCLC and regulated cancer cell invasion and migration." (PMID 31842825, 2019). "In this study, we found that LUADT1 was also upregulated in SCLC and could promote the invasion and migration of cancer cells." (PMID 31842825, 2019). "Therefore, LUADT1 may sponge miR-15a-3p to upregulate Twist1 in SCLC, thereby promoting cancer cell invasion and migration." (PMID 31842825, 2019).
LUADT1 also shares sentences with these, for which no sentence is quoted: small cell lung carcinoma (2 papers); melanoma (1).